CCNF (cyclin F)
Diseases named in the same sentence as CCNF in open-access papers (continued):
Sharing a sentence is not in itself a finding about the gene and the disease.
colon carcinoma (4 papers, 2018 to 2021). "In this study, we identified six cyclin genes (CCNA2, CCNB1, CCND1, CCNE1, CCNF, and CCNJL) that are potential diagnostic biomarkers of colon cancer." (PMID 33996604, 2021). "Given the potential of the four important cyclin genes (CCNA2, CCNB1, CCNE1, and CCNF), we further investigated the genes co-expressed with them in colon cancer via WGCNA." (PMID 33996604, 2021). "It is worth noting that in 5-FU-resistant colon cancer cell lines, the expression of CCNF is significantly upregulated, which is considered to be related to a drug-resistant phenotype." (PMID 34397798, 2021). "It is reported that CCNF is expressed in colon cancer tissue samples and overexpressed as an epigenetic clock gene in colon adenoma tissue samples." (PMID 30186855, 2018). "Overall, patients with lower expression of the four genes (CCNA2, CCNB1, CCNE1, and CCNF) had worse survival outcomes, which implies that these members of the cyclin family might be ideal prognostic biomarkers for colon cancer." (PMID 33996604, 2021). "Among the four datasets of colon cancer from The Cancer Genome Atlas and the Gene Expression Omnibus, six cyclin genes (CCNA2, CCNB1, CCND1, CCNE1, CCNF, and CCNJL) were differentially expressed between normal and tumor tissues." (PMID 33996604, 2021).
liver cancer (4 papers, 2021 to 2024). An epithelial or non-epithelial malignant neoplasm that arises from the liver. "There is a study that had shown that low CCNF expression is associated with poor prognosis of liver cancer, which is also the subject of our research, but our results differ from the previous study and we will discuss the reason in the discussion section." (PMID 34397798, 2021). "Another example is liver cancer, where an elevated level of CCNF was associated with worse OS." (PMID 38654021, 2024). "The differences in somatic mutations between the high expression and low expression groups indirectly confirm that CCNF may play a certain role in the somatic mutation of liver cancer." (PMID 34397798, 2021). "The expression of CCNF in liver cancer tissues was significantly increased compared with that in adjacent tissues, and patients with high CCNF expression had a worse prognosis than those with low CCNF expression." (PMID 34397798, 2021). "Our analysis using online tools showed that mutations in CCNF influence the occurrence and development of some tumors; however, in 372 liver cancer patients, the mutation rate was only 0.81%, so CCNF mutation may not have a significant impact in liver cancer patients." (PMID 34397798, 2021). "Collectively, our study revealed that high CCNF expression may be important for predicting the survival of patients suffering from HCC and that CCNF may serve as a target for the diagnosis and treatment of liver cancer." (PMID 34397798, 2021).
pancreatic adenocarcinoma (4 papers, 2021 to 2024). "Here, the analysis of TCGA dataset of 177 pancreatic adenocarcinoma patients showed that mRNA expression levels of CCNF were significantly elevated in 57.63% of PDACs and associated with more advanced and aggressive tumors and poor patient survival." (PMID 33670609, 2021). "Collectively, the present study is the first to investigate cyclin F and SPDL1 proteins in pancreatic adenocarcinoma, and one of the few that assessed RRM2 in this group of cancer patients." (PMID 33670609, 2021).
skin melanoma (4 papers, 2019 to 2023). "Furthermore, other studies reported that CCNF (an E3 ligase) targets RRM2 (Ribonucleotide reductase M2), a pro-tumorigenic protein, which is linked to poor survival rate in patients with skin melanoma and associated with its protein degradation activity." (PMID 34201347, 2021).
Cognitive impairment (3 papers, 2023 to 2024). Abnormal cognition is characterized by deficits in thinking, reasoning, or remembering. "Nevertheless, our findings broaden the CCNF genetic variant spectrum, and confirm their association with cognitive impairment." (PMID 39766833, 2024). "Clinical presentation is heterogeneous, but CCNF variants are significantly associated to cognitive impairment." (PMID 39766833, 2024). "Finally, more than half of CCNF carriers in our cohort had cognitive impairment, but no patients met the diagnosis criteria of FTD." (PMID 37171577, 2023).
glioblastoma (3 papers, 2019 to 2024). The most malignant astrocytic tumor (WHO grade IV). "Together these observations point out that cyclin F might be a promising target for increasing the efficacy of radiotherapy in glioblastoma and other tumor types." (PMID 39121215, 2024).
lung adenocarcinoma (3 papers, 2019 to 2023). A carcinoma that arises from the lung and is characterized by the presence of malignant glandular epithelial cells. "Moreover, for disease-specific survival (DSS), high CCNF expression significantly contributed to poorer clinical outcomes in KIRC, LIHC, KIRP, LGG, ACC, lung adenocarcinoma (LUAD), MESO, and SKCM." (PMID 37670965, 2023).
pancreatic cancer (3 papers, 2021 to 2023). "In agreement with our studies, CCNF has been recently identified as an upregulated gene in primary pancreatic tumors from Ela-c-myc transgenic mice, compared to both normal pancreas and liver metastatic lesions." (PMID 33670609, 2021).
testicular germ cell tumor (3 papers, 2021 to 2023). A germ cell tumor arising from the testis. "In contrast, upon examining cancer tissues from the TCGA database, CCNF exhibited the highest expression in Testicular Germ Cell Tumors (TGCT), while Kidney Chromophobe (KICH) displayed both the highest and lowest expression levels." (PMID 37670965, 2023).
lung carcinoma (2 papers, 2018 to 2021). "We found that E2F1 regulated genes enriched in ‘cell division’ across all three subtypes, with three target genes in the GO term commonly regulated in lung cancers: CCNF (cyclin F), NCAPH (Non-SMC Condensin I Complex Subunit H), SPAG5 (Sperm Associated Antigen 5)." (PMID 29866045, 2018).
pancreatic ductal adenocarcinoma (2 papers, 2021 to 2023). An infiltrating adenocarcinoma that arises from the epithelial cells of the pancreas. "Of 68 pancreatic ductal adenocarcinomas, 43 (63.24%) demonstrated cyclin F immunoreactivity, while normal pancreatic ductal epithelium was mostly non-reactive (n = 59/65; 90.77%)." (PMID 33670609, 2021).
Primary lateral sclerosis (2 papers, 2016 to 2023). "Diagnosis of primary lateral sclerosis (PLS, an upper motor neuron disease) in a mutation carrier suggests that the spectrum of CCNF-linked motor neuron disease is wider than ALS." (PMID 27080313, 2016).
thymoma (2 papers, 2023). A neoplasm arising from the epithelial cells of the thymus. "Conversely, CCNF served as a low-risk factor in colon adenocarcinoma (COAD) and thymoma (THYM)." (PMID 37670965, 2023). "For instance, in thymoma (THYM), CCNF expression levels exhibited significant positive correlations with Th2 cells, common lymphoid progenitor (CLP), and gamma/delta T cells." (PMID 37670965, 2023).
acute myeloid leukemia (1 paper, 2021). Acute myeloid leukemia (AML) is a group of neoplasms arising from precursor cells committed to the myeloid cell-line differentiation. "Acute myeloid leukemia patients with long-term proliferation demonstrated altered expression of CCNF." (PMID 34112238, 2021).
Anxiety (1 paper, 2023). Intense feelings of nervousness, tension, or panic often arise in response to interpersonal stresses. "Taken together, CCNF_WT and CCNF_S621G mice presented with hyperactivity, reduced anxiety and impaired spatial memory acquisition, reminiscent of clinical symptoms of FTD in the absence of any overt motor impairments." (PMID 36951214, 2023). "Furthermore, while control EGFP preferentially explored the outer zone of the open field arena, 6‐month‐old CCNF_WT and CCNF_S621G mice spent significantly more time in the inner zone, further suggesting reduced anxiety." (PMID 36951214, 2023). "At 3 and 6 months of age, WT and mutant CCNF‐injected mice spent significantly less time in the closed arms compared to EGFP controls with a trend towards increased time spent in the open arms, suggesting reduced anxiety or disinhibition." (PMID 36951214, 2023).
asthma (1 paper, 2024). "With respect to increased risk of asthma, blood genes again had the largest relative effect sizes in males (BAG6, CCNG, CRAT, PTPA, and FAM89B), with female training genes exhibiting the largest effects in ATP6V1G2 in the vastus lateralis, ENDOU in white adipose, and CCNF in blood." (PMID 38693125, 2024).
breast invasive carcinoma (1 paper, 2021). "To evaluate the expression of CCNF in pan-cancer, we searched the TIMER database and found that the CCNF gene is highly expressed in various cancer types, including LIHC, breast invasive carcinoma (BRCA), and bladder urothelial carcinoma (BLCA)." (PMID 34397798, 2021).
breast invasive ductal carcinoma (1 paper, 2019). "Cyclin F is amplified in 10‐15% of breast invasive ductal carcinoma." (PMID 31424118, 2019).
cognitive decline (1 paper, 2018). "However, they did not complete a cognitive function assessment; a follow-up study is still needed to test for a connection between our novel CCNF variants and cognitive decline." (PMID 30008669, 2018).
HIV-1 infection (1 paper, 2017). The type species of lentivirus and the etiologic agent of acquired immunodeficiency syndrome (AIDS). "Understanding the down-regulation of cyclin F in the context of HIV-1 infection in CD4+ T cells is therefore important and necessitates further studies." (PMID 28184007, 2017). "Vif expression was found to be down-modulated with the overexpression of cyclin F and up-regulated with the silencing of cyclin F during HIV-1 infection in both TZM-bl and CEM-GFP cells." (PMID 28184007, 2017). "In a gene expression analysis performed to identify novel gene modulations associated with cell cycle dysregulation during HIV-1 infection in CD4+ T cells, we observed down-regulation of the cyclin F gene (CCNF)." (PMID 28184007, 2017). "On confirming the proteasomal degradation of Vif by cyclin F, we performed in vivo ubiquitination assays of Vif in the presence of cyclin F during HIV-1 infection." (PMID 28184007, 2017). "As HIV-1 infection induces G2/M arrest, it is likely that cyclin F mRNA is down-modulated as a consequence of innate host cell cycle regulation." (PMID 28184007, 2017). "This prompted us to pursue cyclin F characterization and to identify its possible implication in HIV-1 infection." (PMID 28184007, 2017). "We also identified a novel host-pathogen interaction between cyclin F and Vif protein in T cells during HIV-1 infection." (PMID 28184007, 2017). "The down-regulation of cyclin F expression in HIV-1 infection led us to speculate that cyclin F could have a possible role in viral pathogenesis." (PMID 28184007, 2017). "Also, apart from the function we have identified here, we believe that cyclin F could be involved in other cellular mechanisms in the context of HIV-1 infection, which would be interesting to explore." (PMID 28184007, 2017).
ischemic stroke (1 paper, 2020). A stroke disorder caused by obstruction of blood flow to the brain, due to thrombotic (local blood clot formation) or embolic (due to a blood clot or other material traveling from another site) event. "Knockout of TIA1 in neural tissue has been shown to increase expression of CCNF and CDKN1, cell cyclin proteins that are expressed during microglial proliferation after ischemic stroke." (PMID 32327969, 2020).
leukaemia (1 paper, 2020). "The promoter of CCNF and the DMP region of PGP have previously been shown to physically interact, employing CHIA-PET in the K562 leukaemia cell line." (PMID 31988093, 2020).
lymph node metastasis (1 paper, 2024). "Furthermore, overexpression of CCNF in these individuals is associated with a poorer prognosis, advanced T and TNM stage, and distant as well as lymph node metastasis." (PMID 38654021, 2024).
malignant germ cell tumor (1 paper, 2021). A gonadal or extragonadal malignant neoplasm that arises from germ cells. "In malignant germ cell tumors, CCNF participated in the LIN28/let-7 pathway as an oncogene." (PMID 34112238, 2021).
multiple myeloma (1 paper, 2022). "Overexpression of circ-MYBL2 in multiple myeloma cells downregulates the expression of proliferation-related oncogenes by increasing the binding of Cyclin F to MYBL2, which inhibits the activation and phosphorylation of MYBL2." (PMID 35387554, 2022).
non-small cell lung carcinoma (1 paper, 2023). A group of at least three distinct histological types of lung cancer, including non-small cell squamous cell carcinoma, adenocarcinoma, and large cell carcinoma. "Moreover, the downregulation of miR-98-5p often predicts the later clinical stage and distant metastasis of non-small cell lung cancer (NSCLC), indicating that miR-98-5p may be a microRNA that negatively regulates the CCNF gene." (PMID 37168372, 2023).
prostate adenocarcinoma (1 paper, 2023). "Similarly, for progression-free interval (PFI), CCNF was significantly associated with worse clinical outcomes in KIRC, LIHC, KIRP, LGG, ACC, PAAD, prostate adenocarcinoma (PRAD), and MESO, while acting as a protective factor in COAD." (PMID 37670965, 2023).
cancer (28 papers, 2008 to 2025). A tumor composed of atypical neoplastic, often pleomorphic cells that invade other tissues. "Cyclin F (encoded by CCNF gene) has been reported to be implicated in the pathobiology of several human cancers." (PMID 38654021, 2024). "To investigate the prognostic significance of CCNF across different cancer types, we conducted survival association analyses, as well as univariate Cox regression analyses for each cancer." (PMID 37670965, 2023). "Secondly, our study solely provides preliminary evidence of the association between CCNF and pan-cancer." (PMID 37670965, 2023). "In this study, we observed that high CCNF expression in most cancer types is associated with reduced DNA methylation, which can result in tumor genomic hypomethylation." (PMID 37670965, 2023). "In this study, we conducted a comprehensive multi-omics analysis to investigate the intricate association between CCNF and pan-cancer." (PMID 37670965, 2023). "Using the cancer genome atlas (TCGA) repository, CCNF was inversely linked to the expression of miR-30d or miR-30e in LUSC." (PMID 34112238, 2021). "The reduction of cancer suppressor, CCNF, causes uncontrolled cell survival and proliferation, leading to breast carcinogenesis." (PMID 34201347, 2021). "Although their conclusions are contrary to ours, CCNF and its encoded proteins may be potential biomarkers for the diagnosis of cancer." (PMID 37168372, 2023). "Furthermore, CCNF was found to be linked with markers of the tumor immune microenvironment in various cancers." (PMID 37670965, 2023). "Notably, our ROC analysis demonstrated high diagnostic accuracy of CCNF in 17 cancers, with particularly notable performance in CHOL and UCS." (PMID 37670965, 2023). "Moreover, CCNF expression levels positively correlated with Th2 cells, cancer-associated fibroblast (CAFs), follicular helper T cells (Tfh), and myeloid-derived suppressor cells (MDSC) across various immune cells." (PMID 37670965, 2023). "Furthermore, we explored the association between CCNF expression and immune-related genes in pan-cancer." (PMID 37670965, 2023). "However, the specific mechanisms underlying DNA hypomethylation in cancer are currently a subject of extensive debate, necessitating further investigation to elucidate the intricate relationship between DNA methylation and CCNF expression." (PMID 37670965, 2023). "Additionally, the receiver operating characteristic (ROC) analysis demonstrated high diagnostic accuracy for CCNF in 17 cancers, relative diagnostic accuracy in 10 cancers, and low diagnostic accuracy in 4 cancers." (PMID 37670965, 2023). "(A) Cancer Dependency Map data from project Achilles were analyzed to identify the impact of gene loss-of-function on cellular fitness, and fitness correlation with that of CCNF, based on pooled CRISPR/Cas9 gene knockout screens performed in 789 cell lines." (PMID 34851822, 2021). "In addition, cyclin F is downregulated in cancer, and functionally mutated cyclin F is found in neurodegenerative diseases." (PMID 31884567, 2020). "Given the striking synthetic lethality we report, patients with cancers bearing truncating mutations in cyclin F could benefit significantly from treatment with Chk1 inhibitors." (PMID 31424118, 2019). "Additionally, the mutation types of CCNF were further analyzed using the "OncoPrint" module, revealing that CCNF exhibited genetic alterations in 2% of cancer cases, primarily consisting of Amplifications and Deep Deletions, while other alterations were not as significant." (PMID 37670965, 2023). "Furthermore, high CCNF mRNA expression was associated with features of cancer progression." (PMID 33670609, 2021). "Nevertheless, the data indicate that cyclin F is a multifaceted protein with an ambiguous role in cancer cells." (PMID 38654021, 2024).